FGF2 (fibroblast growth factor 2)
Diseases named in the same sentence as FGF2 in open-access papers (continued):
Sharing a sentence is not in itself a finding about the gene and the disease.
tumor (continued). "It will be of interest to assess expression of FGF-2 and its concordance with PDGF receptor expression in CAFs of other tumor types." (PMID 18232728, 2008). "In seeking the mechanism behind the impaired tumor growth and angiogenesis, we found that the production by CAFs of FGF-7, an epithelial cell growth factor, and of FGF-2, an angiogenic factor, was substantively diminished by imatinib." (PMID 18232728, 2008). "A spectrum of angiogenesis stimulators, such as vascular endothelial growth factor and fibroblast growth factor-2 (FGF-2), as well as inhibitors, such as tissue inhibitors of matrix metalloproteinases (MMP), have been detected in NB tumours." (PMID 16721359, 2006). "Mast cells, which are recruited early in tumorigenesis and contribute to angiogenesis and tissue remodeling, have been associated with elevated neovascularization, increased expression of vascular endothelial growth factor and fibroblast growth factor-2 (FGF-2), and overall tumor aggressiveness." (PMID 41401745, 2026). "Additionally, it has been demonstrated that MSCs stimulate tumor angiogenesis by releasing bFGF, VEGF, FGF-2, IL-8, IL-6, IGF-1, TNF, and TGF β." (PMID 39974358, 2025). "There is a tumor suppressor role for SULF1, being an extracellular sulfatase that removes 6-O-sulfate groups from heparan sulfate (HS) chains, thereby reducing the activity of HS-binding growth factors such as FGF2, VEGF, amphiregulin, HB-EGF, and HGF." (PMID 41373732, 2025). "The secreted factors induced by BCAM in tumor cells, and indirectly through the tumor cell secretome in mesothelial cells, likely cooperate to promote angiogenesis, e.g. through VEGFB produced by tumor cells, CXCXL8 expressed by mesothelial cells and FGF2 secreted by both cell types." (PMID 40082910, 2025). "Furthermore, in prostate cancer, downregulation of miR-15/16 in CAFs relieves repression of the FGF2/FGFR1 axis, further promoting tumor growth and metastasis, highlighting the molecular complexity of CAF–tumor cell interactions." (PMID 41514604, 2025). "Our results demonstrate significant downregulation of FGF2 and FGF10 in UCEC, which may contribute to impaired wound healing and reduced tumor progression in these cells." (PMID 39833941, 2025). "In addition to supporting tumor growth, TANs contribute significantly to tumor angiogenesis by releasing proangiogenic factors such as VEGF, prokineticin-2 (Bv8/Prok2), and fibroblast growth factor 2 (FGF2)." (PMID 40805288, 2025). "Additionally, hormone deprivation triggered an upregulation of tumor drug resistance genes ABCB11, BIRC3, FGF2 and NRG1." (PMID 40075208, 2025). "VEGF and FGF2 induce endothelial anergy by suppressing vascular cell adhesion molecule 1 (VCAM‐1) and intercellular adhesion molecule 1 (ICAM‐1) expression, impairing leukocyte extravasation as well as tumour immune surveillance." (PMID 40268524, 2025). "The differentiation of CAFs is crucial for cancer initiation and progression, and it is regulated by signaling pathways induced by tumor cell-derived TGF-β, EGF, PDGFα, PDGFβ, basic fibroblast growth factor (bFGF, also known as FGF2), interleukin 6 (IL-6), and interleukin 1β (IL-1β)." (PMID 40750884, 2025). "In addition to FGF2, ligands such as FGF9 also play roles in microcirculatory regulation, influencing metastatic potential and tumor dynamics, further underscoring the multifaceted role of FGFR signaling in angiogenesis." (PMID 41514604, 2025). "Copper promotes angiogenesis by activating several pro-angiogenic factors, namely vascular endothelial growth factor (VEGF), fibroblast growth factor 2 (FGF2), tumor necrosis factor (TNF), and interleukin-1 (IL-1), thereby promoting tumor initiation, growth, and metastasis." (PMID 40164592, 2025). "Finally, increased FGF–2 levels, further supported by trends in SDF–1α and IL–8, imply activation of pro-angiogenic pathways, which are critical for supporting tumor growth through enhanced nutrient and oxygen delivery." (PMID 41194922, 2025).
tumor (continued). "The number of macrophages (CD68) and all TILs (CD45) were similar irrespective of the FGF2 status in the tumor samples." (PMID 40425576, 2025). "Neutrophils, particularly those polarized toward the N2 phenotype, are key contributors to tumor angiogenesis through the secretion of multiple pro-angiogenic factors, including FGF2, VEGF-A, ANGPT1, CXCL8, HGF, and MMP9, which collectively facilitate tumor vascularization and metastatic spread." (PMID 40564191, 2025). "Studies have shown that FGF2 increases the permeability of endothelial tight junctions and upregulates ICAM-1 and VCAM-1 expression, providing favorable conditions for circulating tumor cell adhesion and transendothelial migration." (PMID 41514604, 2025). "When overexpressed in PitNETs, PTTG1 accelerates cell cycle progression, promotes genetic instability, and activates the expression of growth factors such as fibroblast growth factor 2 (FGF-2) and vascular endothelial growth factor (VEGF), driving angiogenesis and enhancing tumor invasion." (PMID 41573212, 2025). "The results showed significant reductions in VEGFA, FGF2, and ANGPT concentrations in the CAR-M group, suggesting that CAR macrophages might modulate the tumor microenvironment by regulating angiogenic factors." (PMID 39592929, 2024). "Eosinophils may promote tumour angiogenesis by the secretion of angiogenic factors, including the vascular endothelial growth factor (VEGF) and fibroblast growth factor-2 (FGF-2), granulocyte-macrophage colony-stimulating factor (GMCSF), and IL-8." (PMID 38673958, 2024). "Furthermore, it was noted that LMP1 not only encouraged the expression of fibroblast growth factor 2 (FGF‐2), a strong angiogenic factor involved in tumor development and spread in epithelial cells, but moreover caused FGF‐2 release through exosomes." (PMID 39558933, 2024). "Additionally, FGF2 secreted by CAFs can synergize with VEGF to enhance angiogenesis and promote tumor growth." (PMID 39519109, 2024). "Based on the Spearman correlation analysis in GEPIA, we identified a significant correlation between STAT1 and LDHA/LDHB/FGF1/FGF2 in tumor tissues but not in normal tissues." (PMID 38764020, 2024). "In addition, it can promote the expression of FGF-2 and VEGF, which further promote angiogenesis and tumor progression." (PMID 38660262, 2024). "Vascular endothelial growth factor (VEGF) and fibroblast growth factor 2 (FGF2) secreted by tumor cells induce tumor endothelial cells anergy by inhibiting the upregulation of ICAM-1, VCAM-1, and selectins on tumor endothelial cells under inflammatory stimulation." (PMID 39325128, 2024). "Furthermore, the co-expressions of fibroblast growth factor 2 (FGF2) /VEGFR-3 and FGFR-1/PDGF-B in tumor cells were also significant predictors of a poor prognosis." (PMID 38566083, 2024). "Induced by various tumor-secreted cytokines and chemokines, particularly pro-angiogenic factors like VEGF family members and FGF2, this phenotype hinders responsiveness to pro-inflammatory signals, actively downregulating pro-immune adhesion molecules and chemokines." (PMID 38453816, 2024). "Specifically, FGF-2 is a potent pericyte-stimulating factor; by binding to FGFR2, it induces pericyte proliferation and orchestrates PDGFRβ signaling for vascular recruitment, as demonstrated in the tumor context." (PMID 39086395, 2024). "In an experiment involving MC38 xenografts in mice, the use of an anti-FGF2 antibody alone did not impact tumor growth in unirradiated mice." (PMID 38962005, 2024). "In tumor angiogenesis, FGF-1 and FGF-2 promote endothelial cell proliferation." (PMID 38111673, 2024). "FGF2 indirectly promotes the secretion of CXCL14 through the activation of FGFR1/ERK/aryl hydrocarbon receptor (AHR) signaling cascade from pericytes, which in turn induces M2 polarization of TAMs and promotes tumor metastasis." (PMID 38962005, 2024).
tumor (continued). "Therefore, we further detected the expression levels of angiogenesis-related factors VEGF, FGF-2, FMOD, and PDGF-B in tumor tissues by qPCR." (PMID 38331776, 2024). "On the other hand, eosinophils can secrete several pro-angiogenic factors, such as VEGF-A, fibroblast growth factor 2 (FGF-2) and CXCL8/IL-8, which may favor tumor progression." (PMID 39061080, 2024). "Interestingly, circ_0003221 knockdown decreases the protein expression levels of VEGFA and fibroblast growth factor 2 (FGF2), indicating the inhibitory effects of circ_0003221 on tumor angiogenesis." (PMID 38341592, 2024). "As expected, FGF2 treatment always induced the mammary trees typical of branching morphogenesis either on non-tumor or tumor organoids, exposed or not to miR-203." (PMID 37542268, 2023). "Taken together, these data suggest that FGF2, through both DNMT1/ERK-dependent and -independent pathways, potently antagonizes the expression of EC CAMs and chemokines that are important for CTL homing and entry into tumors or tumor-draining lymph nodes." (PMID 37055433, 2023). "It is thought that bFGF primarily acts on TAMs, and by deleting FGF-2, macrophages could be re-polarized to the iNOS+/CD206+ anti-tumor M1 phenotype." (PMID 37631236, 2023). "By modulating miR-33a-5p/FGF2, MCF2L-AS1 exerts a tumor-promotive function in HCC." (PMID 37432067, 2023). "In premenopausal patients (n = 11), six genes were statistically significantly down-regulated in tumour tissue compared to tumour-adjacent tissue: TIMP3 (13.1-fold), ENPP2 (11.4-fold), FGF2 (7.6-fold), CXCL12 (7.5-fold), TIMP2 (5.2-fold), and PDGFRB (4.9-fold change)." (PMID 37509322, 2023). "Importantly, tumours displaying upregulation of activin responsive genes were also enriched for factors that promote SSC self-renewal, including Gdnf, Igf1, and Fgf2, indicating the tumours generate a supportive microenvironment for SSCs." (PMID 37564373, 2023). "Mast cells can affect tumor growth in several ways: They can promote angiogenesis through production of VEGF and Fibroblast Growth Factor 2 (FGF2), and indirectly through degradation of the extracellular matrix, which results in release of additional pro‐angiogenic factors." (PMID 36752151, 2023). "Fibroblast growth factor 2 (FGF2) possesses broad mitogenic and cell survival activities and is involved in multiple biological processes, including embryonic development, cell growth, morphogenesis, tissue repair, tumour growth and invasion." (PMID 36225120, 2023). "MSCs have also been shown to promote tumor angiogenesis through release of VEGF, bFGF, FGF-2, IL-8, IL-6, TNF, IGF-1 and TGF β as well as subsequent transformation into smooth muscle cells and pericytes, coupled with formation of new tumor vessels." (PMID 36926687, 2023). "Furthermore, the tumor-EMC interactions are a factor for the development of metastasis, also unevaluated by our study, where it remains to be seen if FGF2 plays a crucial, if any, role." (PMID 36843751, 2023). "Serine proteases can degrade extracellular matrix proteins as well as growth factors such as epidermal growth factor (EGF), fibroblast growth factor-2 (FGF-2) and hepatocyte growth factor/scatter factor (HGF-SF) and are involved in tumour cell invasion, angiogenesis and metastasis." (PMID 37055381, 2023). "Mast cells are attracted in the tumor microenvironment and promote tumor angiogenesis and lymphangiogenesis by releasing vascular endothelial growth factor (VEGF), fibroblast growth factor-2 (FGF-2), and proteases." (PMID 35140718, 2022). "Knockdown of FGF2 reduced tumor cell growth rates without affecting migration ability compared with the scrambled shRNA–transfected control tumor cells." (PMID 35439170, 2022). "Moreover, exosomes containing LMP1 can induce the expression of angiogenic factors FGF2 and VEGF, which can enhance the proliferation of blood vessel endothelial cells and promote angiogenesis in tumor development." (PMID 35632758, 2022).
tumor (continued). "However, as FGFR1 is also expressed on tumor cells, we here cannot exclude the contribution of the activation of FGFBP1/FGF2/FGFR1 signaling in tumor cells for vessel co-option." (PMID 35951441, 2022). "Moreover, stromal Fgf2 depletion in the TRAMP mouse model of neuroendocrine prostate cancer has been shown to increase survival and decrease tumor growth and metastasis compared to wild-type TRAMP mice." (PMID 36671452, 2022). "Both the FGF2-neutralizing antibody and PD-166866 inhibited the expression levels of p-FGFR1 and FAPα in HSCs, suppressed the recruitment of Gr-1+ MDSCs, decreased the expression of vimentin, and increased the expression of E-cadherin in tumor cells." (PMID 35951441, 2022). "It has been reported that both FGF-2 and VEGF affect the tumor immune landscape." (PMID 35985991, 2022). "CAF is an abundant source of VEGFA and other pro-angiogenetic factors such as platelet-derived growth factor C (PDGFC), fibroblast growth factor 2 (FGF-2), and C-X-C motif chemokine 12 (CXCL12/SDF-1), which directly or indirectly regulates tumor neovascularization." (PMID 35327514, 2022). "This miRNA is also known as a tumor suppressor, as it is negatively correlated with different kinds of cancer, targeting IGF-1R, genes that are involved in the EMT, as well as fibroblast growth factor 2 (FGF2), which plays a role in differentiation and proliferation." (PMID 35955787, 2022). "Similarly, the intervention decreased circulating tumor-promoting growth factors and inflammatory cytokines (i.e., BDNF, TNFα, FGF-2), with greater effects in obese compared to lean rats." (PMID 35725493, 2022). "Fibrinogen binds to growth factors, such as fibroblast growth factor-2 (FGF-2, bFGF) and (VEGF, to enhance tumor growth and increase the migration, invasion, and metastasis of tumor cells, as well as angiogenesis—processes which are considered to be hallmarks of cancer." (PMID 36072935, 2022). "Overall, with this bidimensional analysis we could show that tumor samples were well characterized by high secretions of IL-16, HGF, the TGF-β1, 2 and 3, SCF, FGF-2 and VEGF, and low secretions of CCL8 and Leptin." (PMID 36539890, 2022). "Although higher levels of VASH1 are associated with poorer prognosis for some cancers, this may be due to increased VASH1 feedback in vivo and inhibition of angiogenesis factors (VEGF, FGF-2, and VASH2) in the tumor microenvironment." (PMID 36504559, 2022). "Surprisingly, in both human NPC cells and mouse tumor cells, coculture with FGF-2–stimulated fibroblasts or pericytes did not enhance the tumor migration rate in vitro, suggesting a more complex interaction among cell components." (PMID 35439170, 2022). "FGF-2, together with VEGF and IGF, all secreted by MM plasma cells and inflammatory cells, promotes the recruitment of bone marrow stem cells and progenitor cells into the tumor microenvironment." (PMID 36362718, 2022). "We confirmed via RNA in situ hybridization (ISH) that FGF2 RNA was present in tumor epithelial cells, absent in the microenvironment, and absent in normal nasopharyngeal epithelium." (PMID 35394843, 2022). "No responses were observed in this study and there was no apparent relationship between best tumor response and the presence of FGF2 and FGFR1 protein overexpression or FGFR1 gene amplification." (PMID 34204560, 2021). "Moreover, extracellular AGR2 was observed to directly interact with and enhance the vascular endothelial growth factor (VEGF) and fibroblast growth factor 2 (FGF2), contributing to angiogenesis and tumor growth." (PMID 33413231, 2021). "The tumor growth induced by FGF2 overexpression can be significantly inhibited by the VEGFR2 monoclonal antibody, indicating VEGF’s role as a downstream mediator in FGF2-induced angiogenesis." (PMID 33802841, 2021). "The expression of FGF1 and FGF2 is induced in chronic liver diseases, and their expression levels are increased in more advanced tumor stages." (PMID 33935756, 2021).
tumor (continued). "Additionally, antibodies against FGFR ligands, including anti-FGF2 mAb 3F12E7, and antibodies targeting FGF8b or FGF19, are being investigated as therapeutic approaches to inhibit tumor growth." (PMID 34830951, 2021). "However, more importantly, current anti-angiogenic cancer therapies targeting VEGF-A are confronted with resistance due to upregulation of other growth factors, such as FGF-2, EGF and PDGF by tumor cells." (PMID 34680238, 2021). "PMP tumor tissues were found to be highly vascularized and contained key pro-angiogenic factors, in particular related to vascular endothelial growth factor (VEGF) signaling, but interestingly, high levels of fibroblast growth factor 2 were also detected." (PMID 34198773, 2021). "CAFs originate mainly from the local resident fibroblasts of the tumor, which are activated by tumor cell-derived soluble factors such as transforming growth factor beta (TGFβ), platelet-derived growth factor (PDGF), and fibroblast growth factor 2 (FGF2)." (PMID 34095135, 2021). "In the transcriptional profiling of whole tumor tissues in Ext1CKO and control mice on vascular angiogenesis, Fgf2 and Vegfa expression levels did not change significantly between the two cohorts." (PMID 34790962, 2021). "Finally, using our recently described 3D tumor spheroid model, we were able to demonstrate that subtoxic doses of JQ1 effectively blocked the ability of FGF2 to induce the growth and invasion of ErbBi-resistant and metastatic cells." (PMID 33128042, 2021). "FGF2 upregulates VEGFA expression in various types of cells, including HCC tumor cells." (PMID 33802841, 2021). "Therefore, we used FGF2 and FGF2-overexpressing cells as a proangiogenic stimulus and performed zebrafish yolk membrane (ZFYM) and tumor xenograft (TX) assays, respectively." (PMID 34063734, 2021). "We found that B16F10 cells express substantially higher mRNA levels of the TIE2 ligand Angiopoietin‐2 (Ang2) compared to LLC1 and 4T1 tumor cells, whereas Ang1, Platelet‐Derived Growth Factor Alpha (PDGFA), and Fibroblast Growth Factor2 (FGF2) are similarly expressed (Fig EV1C)." (PMID 34102002, 2021). "RT-PCR analysis of CXCR4, FGF-2, VEGF-A, EGFR, and ERK2 (MAPK1) revealed significantly higher expression of three genes (i.e., CXCR4, FGF-2, and ERK2) in IR/Ipsi-tumor and IR/Contra-tumor groups compared to the control groups." (PMID 34764346, 2021). "FGF2 has been found to have tumor-promoting effects which is not unexpected given its classification as a growth factor." (PMID 35002617, 2021). "Here, the authors show that absence of FGF2 in the tumour microenvironment reduces tumour growth and enhances the anti-tumour immune response by altering macrophage polarization." (PMID 32792542, 2020). "The hypoxia experienced in the tumor induced by the uncontrolled growth of tumor cells, induce the secretion of angiogenesis signals, such as vascular endothelial growth factor (VEGF), fibroblast growth factor-2 (FGF-2), angiopoietins or IL-8, to assure oxygen and nutrient supply." (PMID 32151052, 2020). "FGF2 is a member of the FGF family, which is frequently increased in many malignancies including NSCLC and controls various cellular processes in different contexts, including tumor cell migration and invasion." (PMID 32347652, 2020). "Therefore, our findings suggested that the tumor promoting effects of HOXD-AS1 on CC cell migration and invasion were mediated by the miR-877-3p/FGF2 axis." (PMID 32977766, 2020). "Thus, as reported in human rectal and cervical cancers, radiotherapy led to increased total tumour content of FGF2LMW, and FGF2 was found in TAMs." (PMID 32792542, 2020). "Administration of anti-FGF2 antibody marginally reduced (without statistical significance) the proportion of macrophages in the non-irradiated tumours, but did not alter the increase in CD11b+F4/80+ cells following irradiation." (PMID 32792542, 2020).